PARP1 (poly(ADP-ribose) polymerase 1)
Diseases named in the same sentence as PARP1 in open-access papers (continued):
Sharing a sentence is not in itself a finding about the gene and the disease.
cancer (continued). "Finally, we show that CAM833 inhibits the cellular response to DNA damage, potentiating in BRCA2 wild-type cells the cytotoxic effects both of ionizing radiation or of PARP1 inhibitors, opening future avenues for anti-cancer drug development." (PMID 33662256, 2021). "Supporting this, PARP1 has emerged as a potent cancer target in ovarian and breast cancers." (PMID 35096828, 2021). "FOXM1 and PARP1 were generally overexpressed in various cancer tissues." (PMID 34880209, 2021). "PARP-1, a multifunctional nucleus protein with a multidomain structure, has well documented roles in DNA damage repair, necrosis, apoptosis and DNA damage-dependent cancer progression." (PMID 34440232, 2021). "PARP-1 inhibitors are successfully used in clinic for treatment of different types of cancers." (PMID 34638458, 2021). "Hence, the small molecules developed to improve the current PARP1 inhibitors’ efficacy represent an extremely promising anti-cancer therapy." (PMID 34575883, 2021). "However, RBBP8 has been shown to play a role in the repair of DNA double strand breaks mediated by homologous recombination, which is known to make cancer cells sensitive to PARP1 inhibitors." (PMID 34356665, 2021). "Finally, due to the decreased expression levels or enzymatic activity of PARP1 in cancer cells over time, they naturally grow resistant to PARPi." (PMID 33498235, 2021). "Furthermore, it was reported that a decrease in ERK1/2 and Akt phosphorylation contributes to the inhibition of cancer cell growth via the activation of PARP-1." (PMID 33647882, 2021). "PARP1 became a target in clinical oncology because PARP inhibitors were identified as chemosensitizers in combination with classical DNA-damaging therapies or as mono-therapeutic agents to treat cancers." (PMID 34439361, 2021). "Alternatively, PARP1 might play a important role in the development of various cancers, including cell proliferation, apoptosis, DNA repair, and so forth." (PMID 34285141, 2021). "In breast-cancer susceptibility gene 2 (BRCA2)-deficient cancer cells, the inactivation of replicative stress response factors (e.g. poly (ADP-ribose) polymerase [PARP1] or ATM and Rad3-related [ATR] inhibition) triggers cyclic GMP-AMP synthase (cGAS)-STING-mediated innate immune responses." (PMID 34970273, 2021). "This combination study not only supports the role of ERK activity in ICMT regulation of DNA damage repair activity, but also demonstrates clearly that combined inhibition of MAPK pathway and PARP1 function can be potentially useful in the treatment of this group of cancers." (PMID 34610973, 2021). "In addition to impairing DNA repair, PARP1/PARP2 inhibitors—which are in clinical use against a growing list of cancers—trap the abundant PARP1 protein on DNA breaks, which has genotoxic cytotoxic consequences, especially in BRCA1- or BRCA2-deficient cancers." (PMID 34210965, 2021). "Therefore, for many cancers the synthetic lethality needs to be created by combining PARP1 inhibition with an agent that compromises DNA damage repair or increases DNA damage." (PMID 34610973, 2021). "Hence, to harness the BRCAness-like phenotype of our in vitro CRC model, and with the aim to valorise our newly identified MortaparibPlus as a multimodal anticolorectal-cancer candidate molecule, we next investigated its effect on PARP1 signalling." (PMID 33671256, 2021). "Therefore, PARP1 has become a popular target in the field of cancer therapy and PARP-1 inhibitors have been suggested to be effective to potentiate both chemotherapy and radiotherapy." (PMID 34384442, 2021). "In addition, PARP1 expression was related to p62 expression, suggesting that PARP1 is an upstream molecular regulator of autophagy in human cancers." (PMID 33262410, 2020).
cancer (continued). "In addition to involvement in DNA repair and proliferation, PARP1 participates in the immunomodulatory processes of mononuclear cancer cells." (PMID 32900001, 2020). "Since deregulation of the RB pathway is shared by most human malignancies, we next investigated whether PARP1 may be also involved in the regulation of the RB/E2F pathway in cancer cells." (PMID 33050515, 2020). "Inhibition of PARP-1 significantly promotes the production of ROS in cancer cells after irradiation, which may be related to differences in cell type." (PMID 32862153, 2020). "Little is known about the possible interaction between PARP1 and PD-L1 in human cancers." (PMID 32380691, 2020). "Unlike healthy cells, rapidly proliferating cancer cells are under higher replicative stress, which leads to genomic instability causing PARP1 overexpression." (PMID 32640708, 2020). "Taken together, these findings imply that PARP1 could be a promising target for malignant tumor intervention." (PMID 32774160, 2020). "Therefore, inducing cell death via PARG inhibition and manipulation of the PAR cycle through PARP1/PARG inhibition is an attractive target for cancer therapy." (PMID 32295316, 2020). "Due to the importance of PARP1 for the bulk of PARylation upon DNA damage, RNAi-mediated depletion or single RNA-mediated mutation of PARP1 induces synthetical lethality in BRCA1/2-deficient cancer cells." (PMID 33324554, 2020). "Importantly, there is one more piece of evidence for the contribution of PARP1 to PD-L1-dependent suppression of the immunological response to cancer cells." (PMID 32900001, 2020). "Elucidating an explicit link between PARP‐1 gene rs1136410 C>T and cancer risk no doubt requires a well‐design study with phenotypically homogeneous subjects as well as the inclusion of meticulous analyses of gene‐gene and gene‐environment interactions." (PMID 33108038, 2020). "PARP-1 is the most abundant sensor and effector that responds to a wide variety of stress signals, including inflammatory, oxidative, and metabolic stress in pathological conditions such as cancer and PAH." (PMID 32660602, 2020). "PARP1 may indirectly orchestrate the immune response evasion of cancer cells by affecting the expression of interferon genes in a DSB-dependent manner." (PMID 32900001, 2020). "In fact, inhibition of PARP1—a critical factor involved in DNA damage response and repair of modified DNA bases and SSBs—prior to treatment with NQO1-bioactivatable drug causes a synergistic cancer cell death." (PMID 32974194, 2020). "This discrepancy may be clarified as SCLC is usually detected in a late disease stage and PARP1 mostly acts at later points of cancer development." (PMID 33134168, 2020). "PARP-1 is frequently overexpressed in various types of cancers." (PMID 32344695, 2020). "In addition, PARPis are thought to be toxic to BRCA 1/2-mutant cancers by their ability to trap PARP1 enzyme on DNA." (PMID 32455819, 2020). "Furthermore, in cancer cells, PARP1 represses the anti-inflammatory cytokines IL10 and IL13 as well as PD-L1." (PMID 32900001, 2020). "With high prominence of PARPi in cancer therapy, determining PARP1 expression levels in tumors might help to predict the sensitivity to PARP1-targeted therapy." (PMID 32640708, 2020). "Several trials are ongoing, which are listed in ClinicalTrials.org to study 18F-FTT as a PARP1 tracer pre-/post-treatment, in a wide range of cancers like ovarian (NCT03604315, NCT02637934), breast (NCT03846167), pancreatic (NCT03492164), prostate (NCT03334500), and GBM patients (NCT04221061)." (PMID 32640708, 2020). "Inhibitors targeting BER proteins, such as APE1 and PARP1, are used in cancer therapy." (PMID 32710616, 2020). "Hence, combination treatment consisting of EGFR, cMET, and PARP1 inhibitors posits a novel therapeutic strategy in cancer treatment involving overexpression of PARP1/EGFR/cMET, which are frequent alterations in most solid tumors." (PMID 32295316, 2020).
cancer (continued). "Together, our findings suggest that PARP1/2 dual inhibitors may increase cancer bone metastasis through PARP2-dependent regulation of IMCs, and cause bone loss through PARP1/2-dependent regulation of osteoclasts." (PMID 32221289, 2020). "Currently, targeted radionuclide therapy with PARP-1 is a novel approach for cancer therapy." (PMID 32355263, 2020). "However, we find that CCL2, PARP1 are highly expressed at least in the Basal-type cancers, the majority of which falls into the TNBC category." (PMID 32455851, 2020). "Furthermore, during the last years, PARP1 came into focus in oncology since it represents a promising target of pharmacological PARP inhibitors in various types of cancers." (PMID 32640701, 2020). "PARP1 expression, as well as the level of protein PARylation that usually corresponds to the PARP1 activity, is known to increase the response to proinflammatory stimuli such as LPS or cytokines in cancer cells." (PMID 32900001, 2020). "Indeed, cancers with BRCA1/2 mutations rely on PARP1 for genome integrity, and they are selectively killed by PARP1 inhibitors (PARPi) via the ‘synthetic lethality’ mechanism." (PMID 32844745, 2020). "Notably, NAM primarily seems to exhibit its chemotherapeutic capacity by suppressing SIRT1 and PARP1, as already shown in preclinical models of diverse cancers." (PMID 32245130, 2020). "Here, the authors show that PARP1/2 dual inhibitors may increase cancer bone metastasis through PARP2-dependent regulation of immature myeloid cells, and cause bone loss through PARP1/2-dependent regulation of osteoclasts." (PMID 32221289, 2020). "In basal conditions, PARP1 also regulates transcriptional activity in cancer cells." (PMID 32455851, 2020). "Interestingly, Du and colleagues have shown that cMET, which is a receptor tyrosine kinase, can further stimulate the activity of PARP1 in cancers to survive the lethal effects of ROS-induced DNA damage." (PMID 32295316, 2020). "Meanwhile, a previous related study also indicated the favorable role of PARP1 in cancer development and the fact is that strong PARP activation may result in depletion of NAD+ and ATP which in turn cause cell death." (PMID 33134168, 2020). "Aberrant expression of PARP1 has been recorded in different human cancers." (PMID 33112558, 2020). "Hence, the purpose of this review is to compile and update on important PARP1-targeted radio-theranostics developed recently, in the context of their specific applications in cancer diagnosis and therapy." (PMID 32640708, 2020). "Based on research indicating that inhibition of PARP-1 might sensitize cancer cells to radiotherapy, the function of PARP-1 in DNA repair has been utilized in targeted radiotherapy." (PMID 32355263, 2020). "All in all, the understanding of the biological implications of the interaction between PARP1 and E2F1 could serve as the foundation of novel therapeutic avenues for managing cell cycle deregulation, a hallmark of cancer." (PMID 33050515, 2020). "Studies in the past have shown that PARP inhibition sensitizes cells to ionizing radiation and DNA damaging genotoxic agents irrespective of HR status and the activity of PARP1/2 in cancer cells is critical in the establishment of resistance to genotoxic radio- and chemotherapies." (PMID 33519476, 2020). "Although PARP1 inhibition has been applied in clinical settings in combination with different therapeutic agents, it is still crucial to develop alternative regimens to overcome drug resistance and insufficient efficacy in cancer therapy." (PMID 32093123, 2020). "Mechanistically, defining PARP-1 dependent DNA processing functions is pivotal for the development of successful PARPi therapy and therapeutic regimens in the treatment of several different cancers." (PMID 33053746, 2020).
cancer (continued). "Nevertheless, our evidence now indicates that USP6 and PARP-1 should be considered important factors in the responsiveness of cancer cells to radiation therapy, particularly proton beam therapy that can generate high-LET protons and CDD at the distal end of the Bragg peak." (PMID 30851349, 2019). "Supportive of the hypothesis of increased PARP1 expression in SNP carrying cells is the fact that rs1805407 is in perfect linkage disequilibrium with two PARP1 promoter SNPs (rs2077197 and rs6665208), which overlap ChIP peaks of cancer transcription factors." (PMID 30824778, 2019). "Next, we performed a co-expression analysis to address whether PARP1 expression is correlated to expression of candidate genes in different cancers." (PMID 31105872, 2019). "Importantly, macroH2A1.1 expression is often lost in cancer cells and transformed cell lines, explaining some of the disparate results regarding PARP1’s role in BER seen in the field." (PMID 31636161, 2019). "Integrated analysis of public databases and structural predictions indicated that the two affected individuals also had additional variants in genes including TGFB2, TRAP1, PARP1, and EGF, each potentially relevant to cancer risk alone or in conjunction with the SDHA variant." (PMID 30680959, 2019). "Targeting the poly (ADP-ribose) pathway holds great promise as an approach to anti-cancer therapy, and some success has been met using PARP1/2 inhibitors (PARPiS) to treat cancers harboring defects in the homologous recombination repair pathway, especially BRCA1/2 mutated tumors." (PMID 30459355, 2019). "Overall, based on the pro-tumorigenic effects of PARG activity, and the profound effect of PARG knockdown on tumor growth and metastasis, our data emphasize the potential of PARG inhibition as a rational approach to drugging the PAR pathway, beyond PARP1/2 inhibition, for anti-cancer therapy." (PMID 30459355, 2019). "Knowledge of its interactions could not only help to discover new applications of these inhibitors in different cancers with specific dysregulated pathways related to PARP1." (PMID 31105872, 2019). "Mechanistically, PARP1 inhibitors have been shown to compete with ligand NAD+, inhibit the PARylation of PARP1 or restoration by PARG enzyme resulting in increase in accumulation of DNA double-strand breaks (DSB) leading to growth arrest/apoptosis in cancer cells." (PMID 31856867, 2019). "For this reason, PARP1 inhibitors, like olaparib, trapping PARP1 on the lesion owing to inactivation of its catalytic activity as well as reversing allostery, are approved for use in the treatment of cancers with defective homologous recombination mechanisms." (PMID 30799503, 2019). "Nevertheless, whether PARP1 inhibitors function to treat cancer by inhibiting HR needs to be tested in knock-in mice models for assessing HR efficiency in vivo." (PMID 31291457, 2019). "As PARP1 inhibitors could affect several DNA repair pathways, they are widely used in cancer therapy because this treatment could lead to cancer cell death through a mechanism called “synthetic lethality”." (PMID 31105872, 2019). "The obtained compounds from this study may be potential leads for PARP-1 inhibition in the treatment of cancer." (PMID 31766720, 2019). "PARP1 inhibitors are drugs used in cancer therapy, in particular where DNA repair is defective." (PMID 31105872, 2019). "Therefore, the inhibition of Polθ sensitizes these cells to genotoxic chemicals and PARP1 inhibitor treatment, which indicates Polθ inhibition as a novel cancer therapeutic strategy." (PMID 31109041, 2019). "Poly-ADP-ribose chains were detected in both immunoprecipitated enzymes, i.e., BRG1 and histone acetyltransferase, in the studied cancer lines, thereby providing further evidence for a possible PARP1 role in the regulation of transcriptional activity of BRG1–EP300 complexes." (PMID 31614656, 2019).
cancer (continued). "Furthermore, PARP1 inhibitors have been shown to sensitize cancer cells to other anticancer drugs and hence deemed beneficial for combinatorial therapies." (PMID 31856867, 2019). "High levels of PARP1 in cancer cells promote cell cycle progression, and may in response to proliferation arrest thereby sensitize cells to agents that challenge redox homeostasis." (PMID 31391118, 2019). "Consequently, several PARP1 inhibitors were developed showing promising results, with olaparib being the first one to be approved clinically for treating BRCA1/2 mutated cancers." (PMID 30551210, 2019). "Therefore, inhibition of PARP-1 is a promising therapeutic target for drug development in the context of various forms of ischemia, inflammation and cancer therapy." (PMID 31766720, 2019). "PARP-1 is activated by DNA damage that is inherent to cancer and massive DNA damage may lead to rapid activation of PARP-1 and PAR formation." (PMID 31601918, 2019). "PARP1 role in HR pathway has been recently gained much attention due to attempts towards the development of potent and selective PARP1 inhibitors to suppress DNA repair pathways and induction of cell death in cancer cells with perturbed DNA damage response." (PMID 31423128, 2019). "The role of poly-ADP-ribosylation in the fine-tuning of numerous intracellular processes simultaneously allows the maximization of the effectiveness of PARP1 inhibitors in rendering cancer cells vulnerable to anticancer drugs, which challenge PARP1-dependent or concurrent intracellular routes." (PMID 31614656, 2019). "The addition of a WEE1 inhibitor to olaparib may force cancer cells to proliferate in the presence of PARP1-mediated DNA damages resulting in a massive induction of cell death." (PMID 31717700, 2019). "Thus, PARP1 appears to be involved in both basal processes and response to cellular stresses with implications in human disease, particularly in cancer." (PMID 30991935, 2019). "In addition, we also evaluated the protein levels of PARP1, Bax and Bcl‐2, which are typical apoptotic proteins in cancer cells." (PMID 30920152, 2019). "However, regulation of protein PARylation in cancer remains understudied, as does the potential of targeting members of this pathway beyond PARP1/2." (PMID 30459355, 2019). "However, the PARP-1 (762 Ala) gene variation has also been observed playing a protective function in the initiation of a few cancers in Caucasian populations." (PMID 31609976, 2019). "Our report sheds new light on the still enigmatic molecular functions of DEK and suggests that DEK expression levels may influence the sensitivity of cancer cells to PARP1/2 inhibitors." (PMID 31408463, 2019). "In addition, veliparib exhibits a relatively low ability to trap PARP-1 on DNA and relatively low cellular activity in cancer cells, as compared with other PARP-1 inhibitors." (PMID 31108884, 2019). "PARP1 plays a role in the regulation of multiple transcriptional pathways that may be involved in cancer formation including promotion of cell proliferation." (PMID 30271949, 2018). "Preclinical studies indicate that the attenuation of CCDC6 in cancer confers resistance to cisplatinum and sensitizes the cancer cells to the small molecule inhibitors of Poly (ADP-ribose) polymerase (PARP1/2) in accordance with its role in the DNA damage response." (PMID 29455670, 2018). "To address the role of PARP1 in the response to bulky DNA adducts, we treated human cancer cells with benzo[a]pyrene 7,8-dihydrodiol-9,10-epoxide (BPDE), which represents the active metabolite of the environmental carcinogen benzo[a]pyrene [B(a)P], in nanomolar to low micromolar concentrations." (PMID 29196784, 2018).